SMARCA1 (SNF2 related chromatin remodeling ATPase 1)
Diseases named in the same sentence as SMARCA1 in open-access papers (continued):
Sharing a sentence is not in itself a finding about the gene and the disease.
head and neck squamous cell carcinoma (1 paper, 2022). A squamous cell carcinoma that arises from any of the following anatomic sites: lip and oral cavity, nasal cavity, paranasal sinuses, pharynx, larynx, and salivary glands. "Furthermore, applying multiple deconvolution algorithms helped us obtain a statistically significant positive correlation between SMARCA1 and cancer-associated fibroblasts in BRCA, CESC, COAD, ESCA, head and neck squamous cell carcinoma (HNSC), HNSC-HPV-, PAAD, READ, STAD and TGCT." (PMID 36126083, 2022).
hemangiosarcoma (1 paper, 2009). "It is thus feasible that deregulation of SMARCA1 potentiates susceptibility and/or heritability of hemangiosarcoma in Golden Retrievers." (PMID 19461996, 2009). "Nevertheless, we examined whether the association between expression of TSP-3, DLA-88, or SMARCA-1 and breed (Golden Retriever) would hold in non-hemangiosarcoma samples." (PMID 19461996, 2009). "Upregulation of SMARCA1 in Golden Retrievers with hemangiosarcoma was intriguing since changes in expression of a single transcriptional regulator can create genome-wide disruption of a variety of genes, possibly resulting in faster progression of the disease." (PMID 19461996, 2009). "However, in hemangiosarcoma samples from Golden Retrievers, the expression of TSP-3 and DLA-88 was consistently lower, and the expression of SMARCA1 was consistently higher than in non-Golden Retrievers (p<0.03)." (PMID 19461996, 2009).
leiomyosarcoma (1 paper, 2018). An uncommon, aggressive malignant smooth muscle neoplasm, usually occurring in post-menopausal women. "Leiomyosarcomas were the most common to harbor SMARCA1 genomic alterations, being found in 6 of 99 cases (6%)." (PMID 31093468, 2018). "SMARCA1 expression was intact in all cases of leiomyosarcoma and liposarcoma." (PMID 31093468, 2018).
liposarcoma (1 paper, 2018). A usually painless malignant tumor that arises from adipose tissue. "Of the two cases of liposarcoma and MPNST with SMARCA1 loss, one case each had expression in adjacent normal tissue." (PMID 31093468, 2018). "SMARCA1 deletions were present in only one case of dedifferentiated liposarcoma among 56 cases of liposarcomas (1.7%) and in only one of 48 (2%) undifferentiated sarcomas." (PMID 31093468, 2018). "SMARCA1 was also expressed in all cases of liposarcoma (n=8), dedifferentiated, pleomorphic, and myxoid subtypes." (PMID 31093468, 2018). "SMARCA1 deletions existed in 1/56 dedifferentiated liposarcomas and 1/48 undifferentiated sarcomas." (PMID 31093468, 2018).
Macrocephaly (1 paper, 2023). Occipitofrontal (head) circumference greater than 97th centile compared to appropriate, age matched, sex-matched normal standards. "Individuals carrying SMARCA1 loss-of-function variants exhibited a mild genome-wide DNA methylation profile and a high penetrance of macrocephaly." (PMID 37841849, 2023). "Individuals with pathogenic variants in SMARCA1 are phenotypically distinct in comparison to BPTF and SMARCA5 NDDs, as suggested primarily by the high penetrance of macrocephaly." (PMID 37841849, 2023).
malignant peripheral nerve sheath tumor (1 paper, 2018). Malignant peripheral nerve sheath tumor (MPNST) is a rare and often aggressive soft tissue sarcoma occurring in a wide range of anatomical sites. "Our study is the first to demonstrate loss of expression of SMARCA1 in subtypes of soft tissue sarcomas, including undifferentiated sarcoma and malignant peripheral nerve sheath tumors." (PMID 31093468, 2018).
microcephaly (1 paper, 2023). A congenital or acquired developmental disorder in which the circumference of the head is smaller than normal for the person's age and sex. "Since the ISWI subunits are interchangeable within the NURF complex, the severe microcephaly observed in Smarca5 and Bptf conditional knockouts also suggest that Smarca1 and Smarca5 may regulate brain growth via different mechanisms." (PMID 37841849, 2023).
neuroendocrine tumors of the (1 paper, 2021). "Genes of the SWI/SNF complex were also found to be mutated in more than 20% of neuroendocrine tumors of the lung, including genes of the ARID1 family, BCL11A, SMARCA1, SMARCA2, SMARCA4, SMARCB1, and SMARCC2." (PMID 33641055, 2021).
Nicolaides-Baraitser syndromes (1 paper, 2023). "Given that a clinical continuum is observed in Coffin-Siris and Nicolaides-Baraitser syndromes depending on which BAF encoding gene is mutated, it is not unusual to consider that SMARCA1, SMARCA5, and BPTF NDDs may also align along a clinical spectrum." (PMID 37841849, 2023).
ovarian endometrioid carcinoma (1 paper, 2025). "These included alterations in RAD51C, NOTCH4, SMARCA4, SMARCA1 and JAK1 in ovarian endometrioid carcinomas and SMARCA4 genes in ovarian mucinous carcinomas." (PMID 40981433, 2025).
ovarian mucinous carcinomas (1 paper, 2025). "In addition to identifying genes previously known to be involved in these tumors, we identified alterations in RAD51C, NOTCH4, SMARCA1/4, and JAK1 in ovarian endometrioid, ESR1 in uterine endometrioid, and SMARCA4 in ovarian mucinous carcinomas." (PMID 40981433, 2025).
soft tissue sarcoma (1 paper, 2018). A malignant neoplasm arising from muscle tissue, adipose tissue, blood vessels, fibrous tissue, or other supportive tissues excluding the bones. "This is the first study to demonstrate loss of expression of SMARCA1 in soft tissue sarcomas subtypes, including undifferentiated sarcoma." (PMID 31093468, 2018). "SMARCA1 GAs were present in 8/261 soft tissue sarcomas (3%) in the TCGA dataset." (PMID 31093468, 2018). "Our search of literature revealed there are occasional rare studies on SMARCA1 (SNF2L), and none on SMARCA1 in soft tissue sarcoma." (PMID 31093468, 2018).
soft tissue tumors (1 paper, 2018). "The publically available cBioPortal.32e34 platform was queried to analyze data on soft tissue tumors from The Cancer Genome Atlas project (TCGA) related to SMARCA1 GAs." (PMID 31093468, 2018). "We aimed to evaluate genomic alterations and protein expression of SMARCA1 in soft tissue tumors." (PMID 31093468, 2018). "We aimed to evaluate GAs and protein expression of SMARCA1 in soft tissue tumors." (PMID 31093468, 2018). "SMARCA1 (SNF2L) is another member of the chromatin remodelers, and has not yet been studied in soft tissue tumors." (PMID 31093468, 2018).
undifferentiated sarcomas (1 paper, 2018). "The finding of SMARCA1 IHC loss in undifferentiated sarcoma is in keeping with TCGA molecular alterations." (PMID 31093468, 2018). "SMARCA1 nuclear expression was lost in 3/10 cases (30%) of undifferentiated sarcoma, and 2/5 cases of MPNST (40%)." (PMID 31093468, 2018). "In the 3 cases of undifferentiated sarcoma with loss of SMARCA1, the adjacent normal tissue also did not express SMARCA1." (PMID 31093468, 2018).
uterine cancer (1 paper, 2022). Primary or metastatic malignant neoplasm involving the uterine corpus and/or the cervix. "The highest alteration frequency of SMARCA1 (> 10%) appeared in uterine cancers with “mutation” as the main component." (PMID 36126083, 2022).
cancer (30 papers, 2009 to 2025). A tumor composed of atypical neoplastic, often pleomorphic cells that invade other tissues. "Up to 25% of human cancers carry mutations in at least one of nine SWI/SNF subunit genes including SMARCA1 and 2, SMARCB1, ARID1A/B, PBRM1, and ARID2." (PMID 38085333, 2024). "We found a statistically significant positive relationship between SMARCA1 and the estimated value of cancer-associated fibroblasts infiltration for BRCA, CESC, COAD, ESCA, HNSC, HNSC-HPV-, PAAD, READ, STAD and TGCT (P < 0.05) based on all the algorithms." (PMID 36126083, 2022). "The presence of putative, functional SMARCA1 mutations in both cancer types might point to a broader disruption of chromatin remodelling driving tumor development through altered gene expression in tumor cells." (PMID 40514689, 2025). "Great diagnostic value of SMARCA1 was observed in both cancers." (PMID 36126083, 2022). "We conducted a pan-cancer analysis of SMARCA1 based on the TCGA and GTEx databases and investigated the underlying molecular mechanisms of SMARCA1 in carcinogenesis, clinical prognosis and targeted therapy of various carcinomas." (PMID 36126083, 2022). "SMARCA1, a chromatin remodeling gene, has been reported to stimulate steroidogenic acute regulatory (StAR) protein expression through association with the StAR promoter, and SMARCA1 knockdown causes significant growth inhibition and induces apoptosis of cancer cells." (PMID 22272226, 2012). "Increased exon inclusion in SPPL2A and increased exon exclusion in SMARCA1 were observed in multiple cancer types in the TCGA dataset." (PMID 41198678, 2025). "lncRNA DLEU1 can inhibit CRC cell growth, motility, and invasion, indicating the relevance of the DLEU1/SMARCA1/KPNA3 axis in the etiology of this cancer type." (PMID 37280524, 2023). "This study outlines the pathways mediated by SMARCA1 in different disorders and cancers based on present cell- or animal-experimental evidence." (PMID 36126083, 2022). "We divided the cases into two groups according to high or low expression of SMARCA1 to assess the relationships between SMARCA1 expression and patient prognosis in different cancers, based on the TCGA and GEO databases." (PMID 36126083, 2022). "We used the Kaplan-Meier plotter to evaluate the correlation between SMARCA1 expression and five cancers." (PMID 36126083, 2022). "We started by exploring the potential carcinogenic role of SMARCA1 across 33 carcinomas using the cancer genome atlas (TCGA) and the genotype-tissue expression (GTEx) databases." (PMID 36126083, 2022). "The expression of SMARCA1 varied with each tumor, and so did diagnosis and prognosis, which probably indicates different tumorigenic mechanisms existed in different cancers." (PMID 36126083, 2022). "We also investigated the relationship between SMARCA1 expression and different pathological stages of various cancers via the “pathological stage plot” module of GEPIA2." (PMID 36126083, 2022). "Generally, the top 5 selected genes exhibited a substantial positive reverence to SMARCA1 in most cancer types in a heatmap." (PMID 36126083, 2022). "Using the cBioPortal tool, we obtained the genetic variation status of SMARCA1 across different cancers in the TCGA database." (PMID 36126083, 2022). "Apart from the potential correlation between SMARCA1 and different diseases, especially cancer were revealed by numerous studies." (PMID 36126083, 2022). "Our study presents an initial assessment and illustration of the carcinogenic role of SMARCA1 in different carcinomas." (PMID 36126083, 2022). "It has been found that SMARCA1 regulates normal stem cell or cancer stem cell (CSC) characteristics by interplaying with other types of cofactors." (PMID 34736517, 2021). "Whether SMARCA1 could play an essential role in the carcinogenesis of different cancers through established or undiscovered molecular mechanisms is yet to be determined." (PMID 36126083, 2022).
cancer (continued). "We assessed the link between SMARCA1 gene variation and clinical prognosis of different cancers." (PMID 36126083, 2022). "SMARCA1 deletion has been associated with increased apoptosis through caspase activator Apaf-1 expression upregulation and enhanced proliferation and migration due to WNT signaling regulation in various cancer cells." (PMID 36430148, 2022). "This indicated that SMARCA1 expression might play a critical role in certain cancers through unknown mechanisms." (PMID 36126083, 2022). "Secondly, although we used plenty of databases and tools to elaborate on the role of SMARCA1 on tumorigenesis in many cancers, some of them were still unwell defined, primarily attributing to data updates being out of sync or to each database performing a singular function." (PMID 36126083, 2022). "Hence, we thoroughly evaluated the SMARCA1 gene across all cancers based on several databases including TCGA, GEO, CPTAC and more." (PMID 36126083, 2022). "However, a comprehensive big data-based pan-cancer analysis of the correlation between SMARCA1 and different types of carcinomas is yet to be undertaken." (PMID 36126083, 2022). "Therefore, we used QUANTISEQ, TIMER, MCPCOUNTER, XCELL, CIBERSORT, CIBERSORT-ABS, TIDE and EPIC algorithms to assess the correlation between SMARCA1 expression and the immune infiltration level of different cell types in various of TCGA cancers." (PMID 36126083, 2022). "In our study, we found that DLEU1 interacted with SMARCA1 directly in CRC cells and regulated cancer cell proliferation." (PMID 30098595, 2018). "Strikingly, all of the chromatin remodeling factors (SMARCA1, SMARCA2, SMARCA4 and SMARCA5) are shown to be differentially expressed in diverse cancer cell types." (PMID 26030138, 2015). "SNF2L (SMARCA1), an ATPase chromatin remodeling gene nearly ubiquitously expressed in diverse tissues, cancers, and derived cell lines, contributes to the chromatin remodeling complex that facilitates transcription." (PMID 22577152, 2012). "Other candidates, such as SMARCA1, KDM6B, IRF2, PLK4, and HUWE1, may well have functional relevance to cancer development in particular cancer types, and be worthy of further investigation." (PMID 40514689, 2025). "Although many papers have detailed the correlation between SMARCA1 and different cancers, no pan-cancer analysis has been conducted to date." (PMID 36126083, 2022). "At the time of writing, to the best of our knowledge, no pan-cancer analysis of SMARCA1 has been reported in published literature." (PMID 36126083, 2022). "Until now, the function of SMARCA1 in the type of cancers has not been a focus of research." (PMID 34315468, 2021). "Using the same methods, we obtained a statistically significant negative correlation between SMARCA1 and CD8+ T-cells immune-infiltration in the cancers of HNSC, HNSC-HPV-, LUAD and SARC." (PMID 36126083, 2022). "In blood samples from healthy dogs and dogs with other types of cancers, expression of TSP-3, MHC DLA-88, or SWI/SNF (SMARCA1) was not significantly different among groups." (PMID 19461996, 2009).
tumor (26 papers, 2009 to 2026). "On the contrary, SMARCA1 was also identified as a tumor suppressor, probably “for which loss of expression was found in soft tissue sarcoma and silenced in gastric cancer cells due to aberrant methylation ”." (PMID 36361605, 2022). "We found SMARCA1-associated prognosis to correlate with tumor type and clinical risk factors." (PMID 36126083, 2022). "Furthermore, we explored the relationship between SMARCA1 and tumor mutational burden (TMB) / microsatellite instability (MSI), which were used for the prediction of immunotherapy efficacy." (PMID 36126083, 2022). "Three additional TFs (SMARCA1, DUX4, and CDX1) were identified as potential direct or indirect targets of the HPV genome and were significantly associated with tumor progression in mammalian systems." (PMID 41012596, 2025). "Nevertheless, genes such as Nell2, Smarca1, Slc6a14 and Grhl3 which were highly downregulated by the combined treatment were reported to contribute to tumor progression." (PMID 39450263, 2024). "S116, located in the DB domain of SMARCA1 displays higher phosphorylation levels in primary tumor tissues compared to normal tissues for UCEC and LUAD (all P < 0.001)." (PMID 36126083, 2022). "High SMARCA1 expression in tumor tissues of LUAD was related to poor OS (P = 0.009) and DFS (P = 0.037)." (PMID 36126083, 2022). "Nevertheless, low SMARCA1 expression in tumor tissues of LUSC conversely correlated with a better DFS (P = 0.013)." (PMID 36126083, 2022). "SMARCA1 expression levels were low in tumor tissues whereas results from the DNA methylation level analysis showed that two sites (cg08617833and cg24447042) in the promoter region were negatively correlated with SMARCA1 expression." (PMID 36126083, 2022). "The core ATPase subunit SMARCA1 is ubiquitously expressed in human tissues, but distinct functional roles of SMARCA1, as an oncogenic or tumor suppressor, were observed depending on the tumor types." (PMID 36361605, 2022). "We then used the “similar genes detection” module of GEPIA2 to obtain the top 100 SMARCA1 expression-correlated genes based on tumor types in TCGA." (PMID 36126083, 2022). "Using MEXPRESS, we looked into the potential relationship between SMARCA1 DNA methylation and oncogenesis in different neoplasms." (PMID 36126083, 2022). "We also estimated the correlation between SMARCA1 DNA methylation and protein phosphorylation concerning different neoplasms." (PMID 36126083, 2022). "In contrast, as a tumor suppressor, SMARCA1 is frequently silenced in gastric cancer due to aberrant DNA methylation." (PMID 34736517, 2021). "SMARCA1-noncoding RNA complexes also play a vital role in tumor-initiating cells (TICs) and their properties." (PMID 34736517, 2021). "More studies on regulation and function of SMARCA1 are required to further understand its role in neoplasia and possibly elucidate interaction with other molecules and chromatin remodeling complexes for better therapy." (PMID 31093468, 2018). "Despite our failure to find significant differences based on data in the TIMER2 database, we found that SMARCA1 expression was much higher in tumor tissues than in normal tissues in GBM and LGG based on the GEPIA2 data (combined TCGA and GTEx database) (P < 0.001)." (PMID 36126083, 2022). "Although big data cannot give sufficient evidence to support the tumor oncogenic role of SMARCA1 in the prognosis of LIHC as yet, further studies might influence the results." (PMID 36126083, 2022). "The poorer prognosis of KIRC, KIRP, KICH and UCEC were correlated with lower expression of SMARCA1, which was also down-regulated in tumor tissues, indicating that low SMARCA1 expression might be an independent risk factor for genitourinary." (PMID 36126083, 2022). "SMARCA1 plays an oncogenic or a tumor suppressor role, depending on tumor type." (PMID 34736517, 2021). "The role of SMARCA1 needs to be further explored in the differentiation process and neoplasia." (PMID 31093468, 2018).
tumor (continued). "However, SMARCA1 protein expression was unexpectedly elevated in tumor tissues." (PMID 36126083, 2022). "Therefore, changing the balance of SMARCA5 and SMARCA1 levels could be a potential therapeutic strategy after confirming their opposing expression levels and functions in one given tumor." (PMID 34736517, 2021). "In colorectal cancer, the SMARCA1-NURF complex is recruited by lnc-DLEU1 to the KPNA3 promoter and initiates KPNA3 expression via H3K27ac enrichment, which promotes tumor cell proliferation and migration." (PMID 34736517, 2021). "This SMARCA1-NURF complex is also recruited by another lncRNA, lnc-DLEU1, to the KPNA3 promoter in colorectal cancer, where it initiates KPNA3 expression via H3K27ac enrichment and promotes tumor cell proliferation and migration." (PMID 37175555, 2023). "SMARCA1 (SNF2L) is another member of the chromatin remodelers, and has not yet been studied in neoplasia." (PMID 31093468, 2018). "Interestingly, higher SMARCA1 expression was associated with better DFS based on the GEPIA2 database regardless of the low expression of SMARCA1 in tumor tissues of COAD verified by TIMER2 and Oncomine." (PMID 36126083, 2022). "The expression of SMARCA1 was significantly elevated in some tumor types but not in others." (PMID 36126083, 2022).
infection (2 papers, 2017 to 2025). The state of being infected such as from the introduction of a foreign agent such as serum, vaccine, antigenic substance or organism. "Furthermore, the transcription factor SMARCA1, which is usually a nuclear protein, was greatly enriched in infected cells compared with the uninfected cells, suggesting that its localization changes during infection." (PMID 40207930, 2025).